CXCR2 (C-X-C motif chemokine receptor 2)
Diseases named in the same sentence as CXCR2 in open-access papers (continued):
Sharing a sentence is not in itself a finding about the gene and the disease.
tumor (continued). "The correlation of CXCR2 levels with immune checkpoint markers might represent an attempt of the body to counteract tumor progression." (PMID 34066060, 2021). "Additionally, we reviewed the mechanisms of proinflammatory cytokines, such as C-X-C motif ligand 8 (CXCL8) and its cognate receptor, C-X-C chemokine receptor 2 (CXCR2), in contributing to tumorigenesis and tumor progression." (PMID 34640631, 2021). "Furthermore, in an in vivo model of pancreatic cancer, IFNγ treatment was shown to inhibit CXCL8 expression on tumor cells, reducing trafficking of suppressive CXCR2+CD68+ macrophages to the TME, restoring immune activity and response to anti-PD-1 therapy." (PMID 33801234, 2021). "Moreover, serum levels of CXCL8, CXCR2 and classical tumor markers were higher in Lauren type 2 than in patients with Lauren type 1, while CRP concentrations were the highest in patients with Lauren type 1." (PMID 34680333, 2021). "The result of IHC suggested inhibition of CXCR2 could decrease neutrophil infiltration and attenuate immunosuppression in tumor microenvironment with decreased levels of TGF-β and Arg-1." (PMID 33814009, 2021). "The data makes blockade of CXCR2 a promising anti-tumor strategy." (PMID 33814009, 2021). "In turn, these ELR+ chemokines promote CSC enrichment through CXCR-2 signaling on tumor cells." (PMID 33276524, 2020). "Serum concentrations of both specific receptors for chemokines (CXCR4, p < 0.001 and CXCR2, p = 0.01) as well as the classical tumor marker (CEA, p < 0.001) and the marker of inflammation (CRP, p < 0.001) were statistically significantly higher in PC patients when compared to healthy volunteers." (PMID 32867211, 2020). "Although CXCR2 is highly expressed by cells in the tumor stroma, tumor expression of CXCR2 has also been observed in various genetic models and may drive autocrine or paracrine growth." (PMID 33304355, 2020). "The axis of GATA3/FMNL1/CXCR2 may present a promising therapeutic target for tumor metastasis in ccRCC." (PMID 33324547, 2020). "CXCR2+ MDSC promoted tumour expansion, metastasis, EMT, and T-cell exhaustion in breast cancer." (PMID 32121014, 2020). "To confirm whether CXCR2 signaling is involved in Panc02 orthotopic tumor growth, we examined the effect of the CXCR2 antagonist SB225002." (PMID 32340025, 2020). "Activation of the CXCR1/CXCR2 pathway and the CXCR4/CXCR7 pathway is associated with tumor aggressiveness and poor prognosis; the CXCR3 and CXCR5 axes play a role in tumor suppression; and common variants encoding the CXC chemokine gene have also been studied as biomarkers of CRC." (PMID 32774427, 2020). "The binding of IL-8 to CXCR1/CXCR2 was shown to induce the transition from an epithelial-like to mesenchymal-like status, thus promoting the migration, invasion, and reconstitution of a secondary tumor." (PMID 33256070, 2020). "Moreover, CXCR2 ligands (CXCL1, 2, and 5) induced by TNF-α-activated MSC recruit CXCR2+ neutrophils into tumor, responsible for the pro-metastatic effect of MSC." (PMID 32499779, 2020). "This notion may be supported by the observation that CXCR2 inhibition suppressed tumor development and progression together with decreased TANs in several mouse tumor models." (PMID 32422991, 2020). "Based on the presented findings, we may conclude that serum CXCR4 is a better candidate for a tumor marker than CXCR2 in the diagnosis of PC, while serum CXCR2 is a significant predictor of PC risk." (PMID 32867211, 2020). "Current literatures showed that FMNL1 incorporates with HDAC1 to facilitate tumor metastasis and that CXCR2 expression could be modulated by HDAC proteins." (PMID 33324547, 2020). "Hence, CXCR2 has a critical role in the mechanism of necroptosis-enhanced tumor migration and invasion." (PMID 31999765, 2020). "In our study, CXCR2 was also expressed strongly at the invasive front of the tumor." (PMID 31999765, 2020).
tumor (continued). "As VM is independent of angiogenesis, malignant tumors, such as GBM, which use this mechanism of vascularization, may display therapeutic resistance to antiangiogenic therapies (AAT), especially CXCR2-expressing tumor cells." (PMID 32456359, 2020). "However, CXCL1 and CXCR2 are also upregulated in different tumor tissues and induce tumor angiogenesis." (PMID 33614496, 2020). "Hence, the disruption of CXCR2 will probably inhibit MDSC trafficking into the tumor bed and increase the response to anti-PD1 therapy." (PMID 32867025, 2020). "CXCR2+ MDSCs promoted tumor expansion and metastasis in breast cancer." (PMID 33613512, 2020). "In turn, IL-6 induces the production of CXCL7 by MSCs, which has been shown to promote tumor invasiveness and metastasis in murine models, as well as tumor growth through interaction with the tumor receptor CXCR2 that, in turn, induces the synthesis of other cytokines including IL-6 and IL-8." (PMID 33059744, 2020). "Blocking CXCR2 on MDSCs has shown to increase the efficacy of tumor regression in CCR2 KO mice." (PMID 33374595, 2020). "Moreover, parenchymal PMN–MDSC in human renal cell cancer, have a positive correlation with IL1-β, CXCL8, CXCL5 and CCL3 and CXCR2 blockade reduced tumor weight with enhanced CD4+ and CD8+ T-cell infiltration in renal cell carcinoma-bearing mice." (PMID 32422991, 2020). "It has been shown that CXCR2 is a pro-tumorigenic chemokine receptor that might induce inflammation in the tumor microenvironment." (PMID 32867211, 2020). "Consistently, the CXCR2 inhibitor retarded the tumour growth." (PMID 32778818, 2020). "This could be especially beneficial in cases with known CRD (either systemic or localised, tumour specific alteration of the circadian molecular clock) where the CXCR2 driven mechanisms are accelerated, as our results show." (PMID 32581213, 2020). "Notably, CXCR2 blockade inhibited tumor progression in various tumor models and restored the sensitivity of highly refractory tumor models to immunotherapy, a testimony for a key role of PMN-MDSCs in immunosuppression and resistance to cancer immunotherapy." (PMID 32296575, 2020). "Indeed, it was found that although targeting CCR2+ TAMs or CXCR2+ TANs alone can enhance anti-tumor immunity, unfortunately, this leads to a compensatory influx of alternative myeloid subset, which result persistent immunosuppressive TME." (PMID 33224886, 2020). "Furthermore, interaction between CXCR2 and tumor microenvironment has been demonstrated to be of critical importance for tumor progression." (PMID 32867211, 2020). "Acrolein stimulated cell migration of Müller glial cells through induction of C-X-C motif chemokine ligand 1 (CXCL1) protein, a member of the C-X-C family of chemokines that promotes neutrophil and tumor cell migration through binding to the receptor C-X-C motif chemokine receptor 2 (CXCR2)." (PMID 33193419, 2020). "Genetic deletion of CXCR2 impaired the recruitment of G-MDSCs to the primary tumor in vivo." (PMID 32443699, 2020). "Consistent with a previous report, CXCR2 expression was evident at the invasive front of the tumor." (PMID 31999765, 2020). "However, significant differences were indicated only between serum levels of the analysed receptors (CXCR4 and CXCR2) in all the studied subgroups of PC patients (tumor stage, T, N, M factor) and control groups." (PMID 32867211, 2020). "CXCR1 or CXCR2 modified CAR T cells were capable of tumor regression in the GBM preclinical model." (PMID 33224149, 2020). "Indeed, preclinical studies have shown that combination of anti-PD-1 inhibitor with anti-CXCR2 treatment has synergistic effect to delay tumor growth." (PMID 33101283, 2020). "However, such markers are not specific to TANs and are shared by other immune cells or even tumor cells, such as CXCR2." (PMID 31616408, 2019). "CXCR2 and its ligands are influential targets involved in tumor growth and regulation." (PMID 31788042, 2019).
tumor (continued). "Inhibition of CXC chemokine receptor type 2 (CXCR2), a G-protein-coupled receptor, blocked the tumor angiogenesis via downregulation of connective tissue growth factor (Ctgf) expression in the tumor-associated fibroblasts (TAFs), leading to an anti-tumor effect and significant survival extension." (PMID 30659170, 2019). "The results showed that the proliferative activity of MDPs was similar between WT and CXCR2−/− tumor-bearing mice, suggesting that the CXCR2 deficiency did not impair the proliferative activity of MDPs." (PMID 31395859, 2019). "Furthermore, neutrophils, myeloid cells and bone marrow-derived suppressor cells express CXCR2 and assist in tumor cell proliferation." (PMID 31788042, 2019). "Similarly, a study showed that inhibition with anti-CXCR2 and anti-PD-1 synergistically inhibits tumor formation." (PMID 31540435, 2019). "Thus, our results suggest that the tumor cells require CXCR2 expression for their ability to survive in the bone microenvironment and the effect of depletion of CXCR2 on tumor growth is dependent on the host microenvironment." (PMID 30871004, 2019). "Meanwhile, heterozygous Cxcr2 knockout in endothelial cells of blood vessels may block tumor angiogenesis during the PDAC progression in PKF2h mice." (PMID 30659170, 2019). "We therefore investigated whether these chemokines affected tumor growth and lymphatic invasion via CXCR2." (PMID 31390756, 2019). "Therefore, genetic engineering of ex vivo expanded NK cells to express chemokine receptor such as CXCR2 represents a novel strategy to improve anti-tumor effects following adoptive transfer of NK cells." (PMID 30805309, 2019). "Overall, several studies have reported that CXCR2 is a tumor-stimulating receptor that could be exploited as a marker of poor prognosis in a variety of cancer types." (PMID 31788042, 2019). "The results showed that normal myelopoiesis was not affected in CXCR2−/− mice, however, the number of mo-MDSCs were all significantly reduced in CXCR2−/− mice bearing tumors after 3 weeks, indicating that CXCR2 was required for mo-MDSCs expansion under tumor conditions." (PMID 31395859, 2019). "CXCR2 targeting inhibits tumor growth also because it affects myeloid cell infiltration." (PMID 30894861, 2019). "This stromal ablation of CXCR2 inhibited tumor growth, reduced immunosuppression by lowering infiltration of MDSCs, and reduced angiogenesis, but also increased the fibrotic reaction in the primary tumor and increased metastasis." (PMID 30832219, 2019). "In cancer, the CXCR2 axis is the primary player for neutrophil recruitment to the tumor sites." (PMID 31010242, 2019). "Thus, our findings identify CXCR2 as a potential pharmaceutical target for the inhibition of tumor progression." (PMID 31395859, 2019). "It was hypothesized that CXCR2 is involved in the paracrine loop between tumor cells and its surroundings, which potentiates invasion and metastasis." (PMID 31788042, 2019). "Interestingly, CXCR2 antagonism by AZD5069 is ineffective in preventing Ly6G+ cell recruitment to tumor lesions at latter timepoints." (PMID 31293583, 2019). "Furthermore, knocking down CXCR2 in the host significantly reduced tumor growth by reducing angiogenesis, proliferation, and enhancing apoptosis." (PMID 31562303, 2019). "Since therapeutic effects of CXCR2 inhibition may also be explained by its direct action on tumor cells, future studies are needed to determine the contribution of neutrophils to CXCR2 inhibition-related therapeutic effects." (PMID 31616408, 2019). "HNSCC is the second and RCC the seventh tumor type expressing the highest amount of CXCR2." (PMID 31410218, 2019). "Moreover, the combination of paclitaxel treatment and the inhibition of CXCR2 slows breast tumor growth, attenuates tumor angiogenesis and lung metastasis, and diminishes the number of CSCs." (PMID 31788042, 2019).
tumor (continued). "For understanding the role of tumor cell-derived CXCR2, we utilized Cl66 CXCR2 knockdown (Cl66-shCXCR2) and Cl66-Control cells (Cl66-Control) and observed a significant decrease in tumor growth and tumor-induced osteolysis in Cl66-shCXCR2 cells in comparison with the Cl66-Control cells." (PMID 30871004, 2019). "Forced expression of CXCR2, by lentiviral transduction, could facilitate NK cell migration toward tumor microenvironment possessing its cognate ligands." (PMID 31024520, 2019). "Next, the impact of CXCR2 blockade on anti-tumor efficacy was assessed." (PMID 31753028, 2019). "We hypothesized that co-expression of the IL-8 chemokine receptors CXCR1 or CXCR2 would enhance CAR T-cell migration towards tumor cells and thereby further improve therapeutic activity." (PMID 31091832, 2019). "However, when the mo-MDSCs were supplemented in CXCR2−/− tumor-bearing mice, the number of lung metastatic nodules was increased compared with the CXCR2−/− tumor-bearing mice." (PMID 31395859, 2019). "Thus, combinatorial therapy targeting both CSF1R and CXCR2 seems to have more chances to generate an effective anti-tumor T cell response." (PMID 31447834, 2019). "In addition, the CXCR2/CXCL5 pair has been shown to enhance tumour progression by increasing the formation, recruitment and suppressive activity of MDSCs." (PMID 31010082, 2019). "This may reflect the promiscuity of CXCR2, enabling it to also respond to other tumor-derived ELR chemokine ligands, such as CXCL1/GROα." (PMID 31091832, 2019). "Moreover, T-cells that co-express the A20-28z CAR together with CXCR2 achieved improved tumor control in vivo compared to CAR T-cells that lack this chemokine receptor, without associated toxicity." (PMID 31091832, 2019). "In addition, the substituted 1H-1,3,4-triazol derivative 1e performed well in CXCR2 antagonism and showed good anti-metastatic activity in in vitro anti-tumour metastatic assay." (PMID 30109074, 2018). "Mip-2α may induce CRC tumor cell proliferation in a CXCR2-dependent manner and also promote melanoma growth and metastasis." (PMID 30298062, 2018). "This outcome suggests that therapy targeting, in part, chemokine receptor pathways including Cxcl1/Cxcr2, may be an effective approach for reducing or preventing the tumor-promoting effect of the inflammatory TME." (PMID 29487713, 2018). "The resistance to anti-tumor effect of romidepsin in CXCR2-positive cells might be due to the over-amplification of phosphorylated Akt." (PMID 29515768, 2018). "Due to its role in recruiting myeloid cells to the tumor microenvironment and to the metastatic niche, CXCR2 may be engaged in tumorigenesis and the metastatic process." (PMID 29599927, 2018). "No conserved miR-6868-5p binding sites were identified in the 3’-UTR region of IL-8, excluding that IL-8 was directly targeted by miR-6868-5p, IL-8, also known as CXCL8, has been well documented to promote tumor angiogenesis mainly by binding to its receptor CXCR2." (PMID 30486864, 2018). "Furthermore, CXCL6, CXCL7 and CXCR2 were down‐regulated in Gal‐3‐knockdown tumour spheres, while CXCR2 overexpression in Gal‐3‐knockdown RCC restored the ability of sphere formation." (PMID 30246456, 2018). "In addition, CXCR2+ neutrophils induce the migration of myeloid-derived suppressor cells into tumours." (PMID 29661142, 2018). "Hence, we investigated the efficacy of the pharmacological antagonist of the CXCR1 and CXCR2 on 3D tumor spheroid growth and invasion." (PMID 30086759, 2018). "This could explain the down-modulation of CXCR2 in the ligand-rich tumor microenvironment, a phenomenon we have observed by exposing CXCR2-positive NK cells to recombinant CXCL8 (data not shown)." (PMID 28923105, 2017). "However, tumor-infiltrating NK cells from RCC patients expressed lower CXCR2 compared with peripheral blood NK cells." (PMID 28923105, 2017).
tumor (continued). "Additionally, it has been verified that CXCR2-positive neutrophils can be induced by mesenchymal stromal cells to facilitate cancer metastasis in tumor lesions." (PMID 28415702, 2017). "Moreover, tumor-infiltrating NK cells from RCC patients had reduced CXCR2 expression compared with NK cell in the peripheral blood." (PMID 28923105, 2017). "The maximum tolerated chemotherapy enhanced STAT-1 and NF-κB activity in carcinoma-associated fibroblasts, leading to secretion of ELR motif–positive (ELR+) chemokines, which signal through CXCR-2 on carcinoma cells to trigger them to converse to tumor-initiating cells." (PMID 28328969, 2017). "This indicates that the function of CXCR2 in these two kinds of tumor is regulated by different pathways and the source of ligands maybe from the tumor cells." (PMID 28415702, 2017). "Thus, re-expression of CXCR2 through genetic engineering of ex vivo expanded NK cells represents a novel strategy to improve anti-tumor responses following adoptive transfer of NK cells." (PMID 28923105, 2017). "The enrichment analysis also demonstrates activation of the IL-8/CXCR1/CXCR2 pathway in the BM cells that are crucial for the activation of multiple intracellular signaling pathways to regulate proliferation, differentiation, and migration of tumor cells." (PMID 28626727, 2017). "Both blocking CXCL1/CXCR2 signaling pathway and depleting neutrophils decreased tumor burden." (PMID 29179487, 2017). "Importantly, studies have demonstrated critical role of CXCR1 and CXCR2 in tumor growth and metastasis and serves as the key target for the development of novel therapies." (PMID 28484461, 2017). "Although the function of CXCL5/CXCR2 on tumor metastasis is confirmed in vivo." (PMID 28356111, 2017). "Cancer cells facilitate recruitment of tumor-associated neutrophils (TANs) by expressing various of chemokines and cytokines, including CXCL5, CXCL6, and CXCL839, along with ligands that recognize receptors such as CXCR2 expressed by TANs40." (PMID 28223716, 2017). "Furthermore, Tumor Necrosis Factor Alfa (TNF-α) activates MSCs to secrete chemokine (C-C motif) ligand 5 (CCL5), C-C chemokine receptor type 2 (CCR2), and the interleukin 8 receptor, beta (CXCR2) ligands that in turn recruit CXCR2+ neutrophils into the tumor." (PMID 28473858, 2017). "Neutrophils, which have potentials in promoting tumor growth and metastasis, were recruited by CXCL1/CXCR2 axis after liver IR injury and took part in facilitating tumor recurrence as proven by neutrophil-depletion-mediated protection against tumor cells invading." (PMID 29179487, 2017). "Thus high CXCR2 expression in tumor tissue appears predictive of a poor prognosis in patients with solid tumors." (PMID 29312644, 2017). "Consistently, the number of CXCR2+ MDSCs in 1g spleen and 1g primary tumor was also higher in mice with lymph node metastatic (32104.2 ± 3888.7 vs 22673.2 ± 1950.3 in 1g spleen, 8000.0 ± 1059.4 vs 4476.6 ± 1016.4 in 1g primary tumor)." (PMID 29383101, 2017). "Cumulatively, and combined with previous reports from our laboratory, these correlative data suggest that the CXCL1/CXCR2 chemokine signaling axis may be a principal driver of gMDSC recruitment into the MOC tumor microenvironment." (PMID 28915554, 2017). "It seems that CXCL1/CXCR2 signaling activated hepatic microenvironment and increased the susceptibility to recurrence rather than directly chemotactical attraction of tumor cells towards the liver." (PMID 29179487, 2017). "Thus, CXCR2 blockers were proposed to improve the efficacy of chemotherapy by blocking this paracrine reaction in the tumor stroma." (PMID 29081734, 2017). "Since RAS is a crucial signaling pathway known to regulate the homeostatic proliferation of normal cells, it was important for us to evaluate if the CXCR2 antagonists provide a selective growth disadvantage to mutant KRAS-bearing tumor cells versus normal cells." (PMID 26771140, 2016).